AKT3 (AKT serine/threonine kinase 3)
Description:
AKT3 is one of 3 closely related serine/threonine-protein kinases (AKT1, AKT2 and AKT3) called the AKT kinase, and which regulate many processes including metabolism, proliferation, cell survival, growth and angiogenesis. This is mediated through serine and/or threonine phosphorylation of a range of downstream substrates. Over 100 substrate candidates have been reported so far, but for most of them, no isoform specificity has been reported. AKT3 is the least studied AKT isoform. It plays an important role in brain development and is crucial for the viability of malignant glioma cells. AKT3 isoform may also be the key molecule in up-regulation and down-regulation of MMP13 via IL13. Required for the coordination of mitochondrial biogenesis with growth factor-induced increases in cellular energy demands. Down-regulation by RNA interference reduces the expression of the phosphorylated form of BAD, resulting in the induction of caspase-dependent apoptosis.
Synonyms: PKBG; RAC-gamma; PRKBG; MPPH; MPPH2; PKB-GAMMA; RAC-PK-gamma; STK-2
Tractability: Small molecule: a drug acting on it is in phase 2 or 3 trials; a high-quality ligand is known; it belongs to a druggable protein family. Antibody: UniProt places it where antibodies can reach, with high confidence; its Gene Ontology location is reachable by antibodies, with high confidence; the Human Protein Atlas places it where antibodies can reach. PROTAC: it is named in the literature on targeted protein degradation; UniProt records ubiquitination sites on it; ubiquitination databases record sites on it; its protein half-life has been measured; a small molecule that binds it is known.
Target class: AGC protein kinase AKT family; Enzyme; Protein Kinase; AGC protein kinase group; Kinase
Chemical probes: INY-03-041 (high quality), capivasertib (high quality)
Safety:
Unwanted effects reported when the protein is acted on. In parentheses: how it was acted on, where the effect was seen, and who reports it.
heart disease (cardiovascular system; source: Force et al. (2011))
Gene: Protein-coding gene on chromosome 1 (243,488,233 to 243,851,079, reverse strand). Ensembl gene ENSG00000117020.
Subcellular location: Nucleus; Cytoplasm; Membrane
Subcellular location (Human Protein Atlas): Cytosol; Golgi apparatus; Nucleoplasm; Basal body; Plasma membrane; Primary cilium
Pathways (Reactome):
Signal Transduction: AKT phosphorylates targets in the cytosol; AKT phosphorylates targets in the nucleus; Downregulation of ERBB2:ERBB3 signaling; Estrogen-dependent nuclear events downstream of ESR-membrane signaling; G beta:gamma signalling through PI3Kgamma; Inhibition of TSC complex formation by AKT (PKB); MTOR signalling; Negative regulation of the PI3K/AKT network; PIP3 activates AKT signaling; Regulation of PTEN stability and activity; VEGFR2 mediated vascular permeability
Gene expression (Transcription): RUNX2 regulates genes involved in cell migration; Regulation of localization of FOXO transcription factors
Immune System: CD28 dependent PI3K/Akt signaling; Co-inhibition by CTLA4; FLT3 Signaling
Cell Cycle: Cyclin A:Cdk2-associated events at S phase entry; Cyclin E associated events during G1/S transition
Developmental Biology: AKT-mediated inactivation of FOXO1A; Transcriptional and post-translational regulation of MITF-M expression and activity
Disease: Constitutive Signaling by AKT1 E17K in Cancer; SARS-CoV-2 targets host intracellular signalling and regulatory pathways
Cellular responses to stimuli: KEAP1-NFE2L2 pathway
Programmed Cell Death: Activation of BAD and translocation to mitochondria
Vesicle-mediated transport: RAB GEFs exchange GTP for GDP on RABs
Gene Ontology:
Molecular function: ATP binding; protein binding; protein serine/threonine kinase activity; protein kinase activity; protein serine kinase activity
Biological process: negative regulation of cellular senescence; positive regulation of blood vessel endothelial cell migration; positive regulation of cell migration involved in sprouting angiogenesis; positive regulation of endothelial cell proliferation; positive regulation of vascular endothelial cell proliferation; regulation of mitochondrion organization; signal transduction; insulin receptor signaling pathway; intracellular signal transduction; negative regulation of apoptotic process; negative regulation of PERK-mediated unfolded protein response; positive regulation of angiogenesis; positive regulation of artery morphogenesis; positive regulation of cell migration
Cellular component: cytosol; nucleoplasm; cytoplasm; membrane; nucleus
Genetic constraint (gnomAD): Loss-of-function variants: 10 observed, 35.21 expected, observed/expected ratio (o/e) 0.28, 90% interval 0.17 to 0.48. The upper end of that interval is the gene's LOEUF score, 0.48, which puts it in group 2 of 6, group 1 being the genes least tolerant of losing a copy. Missense variants: 139 observed, 358.6 expected, observed/expected ratio (o/e) 0.39, 90% interval 0.34 to 0.45. Synonymous variants: 133 observed, 115.24 expected, observed/expected ratio (o/e) 1.15, 90% interval 1 to 1.33.
Gene-disease validity (ClinGen):
ClinGen rates the evidence that AKT3 causes each of these diseases.
overgrowth syndrome and/or cerebral malformations due to abnormalities in MTOR pathway genes (autosomal dominant): Definitive. A disease caused by mosaic gain-of-function (GoF) of several genes in the MTOR pathway (MTOR, PIK3CA, PIK3R2 and AKT3) are functionally the same despite significant phenotypic variability.
microcephaly (autosomal dominant): Limited. A congenital or acquired developmental disorder in which the circumference of the head is smaller than normal for the person's age and sex.
Homologues: Orthologues: chimpanzee AKT3 (100% identical), macaque AKT3 (100% identical), dog AKT3 (99% identical), mouse Akt3 (99% identical), rabbit AKT3 (99% identical), pig AKT3 (97% identical), rat Akt3 (97% identical), zebrafish akt3a (96% identical), guinea pig AKT3 (94% identical). Paralogues in human: AKT1 (83% identical), AKT2 (77% identical), PRKCQ (40% identical), PRKCD (39% identical), PDPK1 (29% identical).
Diseases named in the same sentence as AKT3 in open-access papers:
AKT3 is named in the same sentence as 245 diseases in open-access papers, as found by Europe PMC text mining. Sharing a sentence is not in itself a finding about the gene and the disease. The quoted sentences say what the papers report.
breast carcinoma (101 papers, 2005 to 2025). "A novel AKT3 mutation was identified in the lesions of HER2-positive breast cancer patients receiving trastuzumab monotherapy." (PMID 38875362, 2024). "Gain of function mutations in AKT3 were discovered in a variety of cancer types, including breast cancer and endometrial cancer, where the PI3K signaling pathway was implicated." (PMID 35443871, 2022). "Previously, AKT3 expression has been linked to tumours of a mesenchymal origin, or to breast cancer cell lines adhering to a more mesenchymal phenotype." (PMID 33673003, 2021). "AKT has three isoforms, AKT1, AKT2 and AKT3, with highly conserved domain structure, which are associated with breast cancer progression and play different roles in breast cancers." (PMID 34503444, 2021). "Similar to Akt1 inhibition, Akt3 deficiency also promotes breast cancer cells migration, invasion and metastasis due to upregulation of S100A4 and increased activation of HER2 and discoidin domain receptor tyrosine kinase 1/2." (PMID 34419139, 2021). "AKT1 and AKT3 are associated with breast cancer invasion, and PTEN-deficient tumors depend on AKT2 for maintenance and survival." (PMID 30837881, 2019). "AKT3 expression in breast cancer is associated with an ER-negative receptor status in breast cancer cell lines and human samples, suggesting AKT3 contributes to aggressiveness in hormone receptor negative breast cancer." (PMID 31752925, 2019). "It is also worth noting that an analogous E17K mutation has been identified in AKT2 in one breast cancer patient and in AKT3 in melanomas." (PMID 27004402, 2016). "It is also important to note that the E17K somatic mutation has also been identified in AKT2 in breast cancer, albeit at lower frequency, and also in AKT3 in human melanoma." (PMID 27004402, 2016). "AKT3 has also been linked to breast cancer proliferation and survival." (PMID 33498407, 2021). "Mutations of AKT2 and AKT3 are rare events in breast cancer with a frequency of 0.4% each." (PMID 31752925, 2019). "Moreover, this newly described translocation of AKT3 predisposes to resistance against the pan-AKT inhibitor MK2206 in breast cancer and to malignant transformation in fibroblasts." (PMID 31752925, 2019). "Increased AKT3 enzymatic activity was found in estrogen receptor-deficient breast cancer and androgen insensitive prostate cancer cell lines, suggesting that AKT3 may contribute to the aggressiveness of steroid hormone-insensitive cancers." (PMID 20604938, 2010). "Of the three AKT isoforms (AKT1, AKT2 and AKT3), AKT1 and AKT2 are the most prominently associated with human breast cancer initiation and progression." (PMID 41408399, 2025). "An increase in AKT3 expression was detected at low frequencies in breast carcinomas, gliomas and hepatocellular carcinomas." (PMID 38358644, 2024). "AKT3 has been reported to be expressed in various cancers, including breast cancers, ovarian cancers, and gliomas." (PMID 38920688, 2024). "In fact, AKT3 is upregulated in ER + breast cancers and androgen-independent prostate cancers, suggesting a role for AKT3 in tumor progression." (PMID 39614261, 2024). "Akt3 is the least studied isoform, most likely due to its low expression and more challenging detection, but more and more studies have emerged, characterizing a specific role of Akt3 in cancer, especially breast cancer." (PMID 38291468, 2024). "For the five FTD-Breast cancer comorbid genes (AKT3, GFAP, C4A, VDAC1, ADCYAP1R1), we analyzed the alterations in the genetic profiles among the different subtypes of Breast cancer." (PMID 37834358, 2023). "AKT3 specifically has been shown to limit the apoptotic response through NF-κB activation; and by alternating AKT3 activity through mi-RNA silencing breast cancer growth is inhibited." (PMID 38033034, 2023). "Overall, we found two novel FTD-COVID-19 comorbid genes, GFAP and RTN4, and five novel FTD-Breast cancer comorbid genes, AKT3, GFAP, ADCYAP1R1, VDAC1, and C4A, in this study." (PMID 37834358, 2023).
breast carcinoma (continued). "In breast cancer, it controls the NF-κB pathway by inhibiting AKT3, and moderated migration, proliferation, invasion, and inducing apoptosis." (PMID 36590916, 2022). "AKT3 is over-expressed in a number of other solid tumours, including breast cancers, and it has been shown to promote cell growth and an epithelial–mesenchymal transition in colorectal and gastric cancer cell lines." (PMID 35406381, 2022). "By using a chronic resistance model of the breast cancer T47D line, we also identified Akt3 as an important mediator of Akt inhibitor resistance." (PMID 36291790, 2022). "RP11–480I12.5 was reported to promote breast cancer growth and tumorigenesis by inhibiting mir-29c-3p mediated degradation of AKT3 and CDK6." (PMID 34026852, 2021). "In the case of breast cancer cells, AKT3 has been reported as a direct target of miR-29b, where its inhibition attenuated the activation of VEGF and c-Myc proteins." (PMID 33833996, 2021). "Our laboratory recently showed an increased bone metastasis without the promotion of osteolysis after generating a knockdown of AKT3 in bone-metastatic breast cancer cells." (PMID 34064589, 2021). "In the murine breast cancer cell line PyMT, the cell–cell adhesion molecule N-cadherin downregulates Akt3 and then reduces cell motility." (PMID 34419139, 2021). "Amplification of AKT1, AKT2 and AKT3 has been reported in gastric, ovarian, pancreatic and breast cancers, glioma and melanoma." (PMID 34419139, 2021). "As HER2, DDR1/2, and EGFR are associated with metastasis of breast cancer, one could assume that the enhanced activity of these receptor tyrosine kinases mediates the enhanced migration, invasion, chemotaxis, and metastasis to bone in the AKT3 knockdown 231-BO cells." (PMID 33670586, 2021). "In this study, we provide evidence that AKT signaling has a crucial role in the metastasis of human breast cancer cells, especially to the bone in an isoform-specific manner in which AKT3 plays the leading role." (PMID 33670586, 2021). "Our data suggest that AKT3 plays a crucial role in the steps of breast cancer metastasis as knockdown of AKT3 in bone-seeking breast cancer cells increases migration, invasion, and chemotaxis towards EGF without affecting cell proliferation." (PMID 33670586, 2021). "For example, a team from the Universität Hamburg, Germany, found that AKT3 silencing contributed to increased invasion and migration of breast cancer cells by activating HER2 and DDR signals." (PMID 34882061, 2021). "For example, in general, basal-like breast carcinoma has been known to harbor mutations involving BRCA1, CCNE1, AKT3, or MYC; however, these genes were largely wild type, and NOTCH1 mutations were relatively common in our SeC-EOs." (PMID 34638295, 2021). "Although Akt3 expression was believed to be restricted to neuronal cells, it is now known that it can also contribute to breast cancer, especially in TNBC." (PMID 34298660, 2021). "It has been reported Akt2 was amplified in 3% of breast cancers and Akt3 is frequently amplified in TNBC." (PMID 34298660, 2021). "While different studies revealed different results regarding the involvement of AKT1 and AKT2 in mammary carcinomas, AKT3 dysfunctions are often correlated with triple negative breast cancer." (PMID 34199634, 2021). "The AKT family consists of the three isoforms AKT1, AKT2, and AKT3, which are shown to be partly inversely correlated in the regulation of breast cancer growth and metastasis." (PMID 33670586, 2021). "Based on TCGA dataset, Akt3 is most amplified followed by Akt2 and amplification of Akt1 was least among Akt isoforms in breast cancer." (PMID 34298660, 2021). "In the TCGA datasets, AKT3 amplification is detected in approximately 10% of breast cancer patients." (PMID 34419139, 2021). "Upregulation of AKT3 mRNA and amplification of Akt3 are reported more frequently in triple negative breast cancer cells than in other breast cancer subtypes." (PMID 33670586, 2021).
breast carcinoma (continued). "Like we have seen in our CMS4 CRC samples, AKT3 activity is more often induced by (over)expression of this gene in a particular group of tumours such as basal-like breast cancer or TNBC, serous ovarian cancer and melanoma." (PMID 33673003, 2021). "Analysis of clinical samples of breast cancer tissues revealed an inverse relationship between miRNA-433 and Akt3 mRNA, the latter being much higher in breast cancer patient samples compared to normal breast tissues." (PMID 34298660, 2021). "It has been reported that Akt3 can contribute to the proliferation of ErbB2 (HER2)-positive breast cancers which express low levels of ERα and contribute to endocrine resistance." (PMID 34298660, 2021). "Akt3 ablation in neu or PyMT oncogene-driven breast cancer mouse models resulted in a mild inhibitory effect on tumour induction." (PMID 33276499, 2020). "It is important to note that in this study on Chinese breast cancer patients the frequency of PIK3R1, AKT1, AKT2, AKT3, and PDK1 mutations was higher than that observed in the TCGA data set." (PMID 32210163, 2020). "The role of AKT1 and AKT3 in breast cancer should be studied as well, because these isoforms have distinctive and non-redundant activities." (PMID 31357505, 2019). "The detection of AKT3 expression in breast cancer-derived DTCs in the human bone marrow suggests a pivotal role of AKT3 in DTCs." (PMID 31752925, 2019). "AKT3 expression was detected only in a subpopulation of breast cancer and its expression is correlated with a TNBC subtype." (PMID 31752925, 2019). "The effect of AKT3 on breast cancer remains mainly unrevealed, but it seems that AKT3 has an anti-migratory function." (PMID 31752925, 2019). "The expression and kinase activity at the protein level mainly depend on the subtype of breast cancer e.g. AKT3 is highly expressed in TNBC, whereas expression of AKT1 correlates with positive ER status." (PMID 31752925, 2019). "Here, we determine that somatic mutations in PIK3CA (44%), PIK3R1 (17%), AKT3 (15%), and PTEN (12%) are prevalent and diverse in Chinese breast cancer patients, with 60 novel mutations identified." (PMID 29636477, 2018). "Isoform-specific Akt abnormalities have been reported in many cancer cells, such as the overexpression of Akt1 in thyroid and non-small cell lung cancers, Akt2 and Akt3 in malignant glioma, and Akt3 in melanoma, ovarian, and breast cancer." (PMID 28483982, 2017). "AKT3 is the most amplified isoform in a range of cancers including glioblastoma, melanoma, endometrial and breast cancers." (PMID 28082369, 2017). "For example, miR-489 has been shown to directly target other oncogenes such as Shp2 in HSCC, SMAD3 in breast cancer, AKT3 in ovarian cancer and Dek in mouse muscle stem cells." (PMID 26918448, 2016). "A MAGI3-AKT3 fusion gene, caused by a chromosomal rearrangement involving breakpoints at MAGI3 intron 9 and AKT3 intron 1, has been previously identified in breast cancer." (PMID 27205883, 2016). "Recently, it has been shown that downregulation of Akt3 in a human breast cancer cell line increased migration in vitro and led to greater lung metastases in vivo." (PMID 27533079, 2016). "In summary, we have demonstrated that knockdown of AKT3 regulates migration in TNBC breast cancer cells via upregulation of S100A4." (PMID 26741489, 2016). "The down-regulation of AKT3 upon interaction with several up-regulated miRs was the highlight observation in the cluster of up-regulated pathways in breast cancers." (PMID 23358700, 2013). "Focusing on a cluster of up-regulated pathways in breast cancers and largely up-regulated miRs we found down-regulated AKT3 that was interacting with a couple of up-regulated miRs." (PMID 23358700, 2013). "By combining these data, we postulated that Akt3 gene is candidate of miR-505-regulating gene, which is responsible for the drug resistance in breast cancer cell." (PMID 22051041, 2011).